EIF3E (eukaryotic translation initiation factor 3 subunit E)
Diseases named in the same sentence as EIF3E in open-access papers:
EIF3E is named in the same sentence as 30 diseases in open-access papers, as found by Europe PMC text mining. Sharing a sentence is not in itself a finding about the gene and the disease. The quoted sentences say what the papers report.
breast cancer (12 papers, 2012 to 2023). A primary or metastatic malignant neoplasm involving the breast. "Another potential gene biomarker in the CNA dataset is EIF3E, a translation factor associated with breast cancer occurrence which is related to EIF3H." (PMID 35205681, 2022). "Surprisingly, eIF3e-deficient breast cancer cells are resistant to these drugs, in contrast to BRCA1-deficient cells." (PMID 33868586, 2021). "Several clinical and experimental observations suggest that altered expression of the eIF3e subunit is associated with the occurrence and development of breast cancer." (PMID 33868586, 2021). "We discovered that eIF3e-deficient breast cancer cells are resistant to PARPi." (PMID 33868586, 2021). "Altered expression of the translation factor eIF3e is associated with breast cancer occurrence." (PMID 33868586, 2021). "Interestingly, reduced expression and loss of heterozygosity (LOH) of eIF3e have been found in human breast cancer and lung cancer." (PMID 22457825, 2012). "These PARP1 and mTORC1 dysfunctions are linked to the induction of cellular senescence, which provides mechanistic insights into how EIF3E protects against breast cancer." (PMID 35205681, 2022). "This study provides mechanistic insights into how eIF3e protects against breast cancer, with potential novel cancer therapeutic opportunities." (PMID 33868586, 2021). "MMTV‐integration events result in the expression of C‐terminal‐truncated eIF3e proteins, leading to mammary tumor formation." (PMID 30087825, 2018). "This suggests that the loss of eIF3e directly results in cancer progression and metastasis as EMT is induced in breast cancer cells." (PMID 28083147, 2016). "In virus-induced murine mammary tumors, the eIF3e gene was identified as a common insertion site and suggested that production of truncated eIF3e could lead to malignant transformation of mammary epithelial cells." (PMID 36830614, 2023). "In search of the underlying mechanism, we found that eIF3e deficiency causes reduced PARP1 expression and mTORC1 hyperactivation that drive breast cancer cells into senescence and secretion of inflammatory factors, providing potential novel cancer therapeutic opportunities." (PMID 33868586, 2021). "In addition, by querying a proteomic resource for breast cancer, we found a significant positive correlation between the eIF3e and PARP1 protein abundances in the triple-negative breast cancer group." (PMID 33868586, 2021). "In breast cancer and lung cancer within the human body, the expression of EIF3E decreases." (PMID 22734884, 2012). "However, the role of eIF3e in breast cancer remains to be better understood." (PMID 33868586, 2021). "The eIF3e gene locus is one of the most frequent integration sites of mouse mammary tumor virus (MMTV), which induces mammary tumors in mice." (PMID 30087825, 2018). "The eIF3e gene locus, also called integration site 6 (Int6), is one of the frequent integration sites of mouse mammary tumor virus (MMTV), which provokes mammary tumor in mice." (PMID 30087825, 2018). "In breast cancer cells, reduction of eIF3e expression by RNAi induces EMT (epithelial-to-mesenchymal transition), suggesting a role of eIF3e in breast cancer metastasis." (PMID 28083147, 2016). "According to the database, we discovered a lower expression of EIF3E and EIF3F in breast cancer." (PMID 35040374, 2022). "EIF3E, another 8q-protein in the RRM2B network, interacts with ATM and BRCA1 for the execution of DNA damage response and EIF3E alterations have been previously observed in breast cancer." (PMID 33868369, 2021). "Although eIF3e silencing results in HR defect also in breast cancer cells, we found that these eIF3e-depleted cells were not sensitive to veliparib treatment, in contrast to BRCA1-depleted cells." (PMID 33868586, 2021).
breast cancer (continued). "For example, EIF3E, which was also translationally down-regulated in MCF7 cells, has been proposed to function as a tumour suppressor and reduced expression has been reported in ~37 % of human breast cancers." (PMID 26589636, 2015).
glioma (6 papers, 2013 to 2023). A benign or malignant brain and spinal cord tumor that arises from glial cells (astrocytes, oligodendrocytes, ependymal cells). "An additional survey study of gliomas that recurred after chemoradiotherapy found an increase in the proportion of tumor cells positive for eIF3e with an upregulated protein expression in the recurrent tumors." (PMID 37522921, 2023). "More studies showed knockdown of EIF3B, decreasing EIF3C, and silencing EIF3D and EIF3E alleviated proliferation and migration of glioma cells." (PMID 32565801, 2020). "In both the CGGA and TCGA datasets, the expression levels of eIF3d, eIF3e, eIF3f, eIF3h and eIF3l highly were associated with the IDH mutant status of gliomas." (PMID 31171919, 2019). "eIF3 subunits show varied expression in distinct regions of GBM tumours. eIF3e proteins expression correlates with glioma grade, highest expression in GBM, and increases in recurrences. eIF3e upregulation in recurrences may have a role in treatment resistance." (PMID 36831575, 2023). "To date, Int6/eIF3e expression in human glioma cells and its role in cell growth have not been studied." (PMID 24481065, 2014).
glioblastoma (5 papers, 2014 to 2022). The most malignant astrocytic tumor (WHO grade IV). "Eight genes associated with glioblastoma prognosis were identified based on LASSO analysis: RPS10, RPS11, RPS19, RSL24D1, RPL39L, EIF3E, NUDT5, and RPF1." (PMID 36733371, 2022). "We highlighted that Int6/eIF3e inhibition through siRNA induces a diminution of glioblastoma cell proliferation through cell cycle arrest and an induction of caspase-dependent and caspase-independent cell death." (PMID 24481065, 2014). "Among these proteins, we found 2,5-phosphodiesterase 12 (Pde12) a negative regulator for antiviral and antitumor functions induced by interferons and Eukaryotic translation initiation factor 3 subunit E (Eif3e) which is essential for proliferation and survival of glioblastoma cells." (PMID 33402730, 2022). "Eight genes—RPS10, RPS11, RPS19, RSL24D1, RPL39L, EIF3E, NUDT5, and RPF—were found to have an expression in the prognosis of glioblastoma." (PMID 36733371, 2022).
ovarian carcinoma (2 papers, 2018 to 2022). A malignant neoplasm originating from the surface ovarian epithelium. "A seven-hub-molecule-signature model (RRAS2, HIST1H2BK, ALB, RPL23A, HIBCH, RPS20, and EIF3E) from those 1198 mtDEPs is established to predict the survival time of ovarian cancer." (PMID 35498135, 2022). "Examination of the resulting network shows that RPS19, PNOC, SFRP1 and KCNJ16 are connected to other frequently altered genes, including MYC or EIF3E as oncogenes, from TCGA ovarian cancer dataset." (PMID 30255801, 2018). "A seven-hub-molecule-signature model (HIBCH, HIST1H2BK, ALB, EIF3E, RPS20, RRAS2, and RPL23A) from a multivariate regression analysis can predict the survival risks of ovarian cancer." (PMID 35498135, 2022).
asthma (1 paper, 2015). "Others have been associated with diabetes (ZBED3), asthma (EMID2), and cancer (FBXO3, HOOK2, MT2A, EIF3E, RPH3AL, PTRF, MT1M, STK32A)." (PMID 25748564, 2015).
breast tumors (1 paper, 2021). "While PARP inhibitors appear as inappropriate drugs for eIF3e-deficient breast tumors, our findings suggest that such cancers may benefit from senolytic drugs or mTORC1 inhibitors." (PMID 33868586, 2021). "Our findings pave the way for new potential therapeutics to treat eIF3e-deficient breast tumors." (PMID 33868586, 2021). "Based on the connection between reduced eIF3e levels and impaired HR, we hypothesized that eIF3e-deficient breast tumors might be vulnerable to PARPi therapy." (PMID 33868586, 2021).
cerebral infarction (1 paper, 2015). An ischemic condition of the brain, producing a persistent focal neurological deficit in the area of distribution of the cerebral arteries. "HIF-2α stabilization by Int6/eIF3e silencing might be a promising methodology in clinical practice for the treatment of ischemic diseases such as CAD, cerebral infarction, and PAD." (PMID 25964891, 2015).
colorectal cancer (1 paper, 2021). A primary or metastatic malignant neoplasm that affects the colon or rectum. "Moreover, they determined that the RSPO2 overexpression was the result of a deletion-mediated gene fusion between exon 1 of EIF3E and exon 2 of RSPO2, the same as described in colorectal cancer." (PMID 34771683, 2021).
developmental delay (1 paper, 2025). "Of note, the genetic variants of EIF4G1 and EIF3E have been linked to PD, while EIF4A2 has been described in pediatric cases with developmental delay and dystonia-tremor syndrome." (PMID 40194557, 2025).
endometriosis (1 paper, 2019). The growth of functional endometrial tissue in anatomic sites outside the uterine body. "In endometriosis, for example, eIF3e-levels are reduced in comparison to healthy endometrium and do correlate with overexpression of E-Cadherin." (PMID 31817792, 2019).
ischemia (1 paper, 2015). A hypoperfusion of the BLOOD through an organ or tissue caused by a PATHOLOGIC CONSTRICTION or obstruction of its BLOOD VESSELS, or an absence of BLOOD CIRCULATION. "The usefulness of eIF3e/Int6 silencing is also evidenced by several studies using ischemia models." (PMID 25964891, 2015).
limb ischemia (1 paper, 2024). A ischemia that involves the limb. "Silencing of EIF3E promotes blood perfusion recovery after limb ischemia through stabilization of hypoxia-inducible factor 2α activity." (PMID 38168759, 2024).
osteoporosis (1 paper, 2021). A condition of reduced bone mass, with decreased cortical thickness and a decrease in the number and size of the trabeculae of cancellous bone (but normal chemical composition), resulting in increased fracture incidence. "Eif3e is an angiogenesis inhibitor and involved in RNA transport, and it is highly expressed in osteoporosis and affects osteoblast apoptosis." (PMID 34249129, 2021).
cancer (16 papers, 2014 to 2025). A tumor composed of atypical neoplastic, often pleomorphic cells that invade other tissues. "Our previous study, primarily performed using HeLa and U2OS cell lines, demonstrated that eIF3e-deficient cancer cells are defective in HR-mediated DNA repair." (PMID 33868586, 2021). "Collectively, these findings suggest that cancer cells deficient for eIF3e prematurely undergo senescence combined with a massive upregulation and secretion of SASP factors." (PMID 33868586, 2021). "Most genes were found related to the development of different cancer types and metastasis, such as MAGI-A23, EIF3E, and SOX5, while PDSD3 was associated to NAFLD." (PMID 40489530, 2025). "To extend our knowledge further on the roles of eIF3e, especially in cancer, we believe it important to consider classification of the loss of function or gain of function of eIF3e." (PMID 30087825, 2018). "Upregulation of eIF3a, eIF3b, eIF3c, eIF3d, eIF3e, eIF3h, and eIF3i along with reduced levels of eIF3e and eIF3f has been observed in several cancers." (PMID 28083147, 2016). "EIF3E(translation initiation factor 3 subunit E) involved in the regulation of cell growth and cell cycle, and is closely related to cancer." (PMID 25955442, 2015). "Levels of nine eIF3 subunits involving eIF3A, eIF3B, eIF3C, eIF3D, eIF3E, eIF3H, eIF3I, eIF3J, and eIF3M were significantly increased in cancer tissues, whereas the eIF3L expression level in tumours was independently decreased than that of normal tissues (p < 0.05)." (PMID 31885740, 2019). "eIF3e was perhaps the first eIF3 subunit the altered expression of which was connected with cancer." (PMID 28981723, 2017). "Essentially, this data suggests that the novel function of eIF3d-eIF3e in maintaining mitochondrial respiration components and serving to adjust metabolic pathways may help us better understand how the cancer-promoting properties of the eIF3 complex emerge." (PMID 28083147, 2016). "Furthermore, a recent study suggests the role of eIF3d-eIF3e module within the eIF3 complex that regulates the translation of specific mRNAs involved in maintaining metabolic pathways that are likely disrupted in cancer cells." (PMID 28083147, 2016). "These included RPL6, RPL7, RPL18A, RPS2, EIF3E, EIF3J, and UBA52, reflecting the elevated protein synthesis demands of cancer cells." (PMID 41228302, 2025). "In the NDRG1 module, PSMD2 is overexpressed in many cancer cells, whereas PABPC1, EIF4G1, EIF3H, EIF3E, and EIF3K are RNA translational control members." (PMID 26735889, 2016). "Except EIF3E and EIF3F found down-regulated and conferred tumor suppressive activity in cancers, majority of EIF3 members including EIF3A, EIF3B, EIF3C, EIF3D, EIF3H, EIF3I and EIF3M were up-regulated and played important roles in tumor progression of multiple cancer types." (PMID 29568350, 2018).
tumor (16 papers, 2012 to 2023). "The gene encoding eIF3e, also called Int6, was first identified as a tumor suppressor gene based on frequent integration of mouse mammary tumor virus (MMTV)." (PMID 25964891, 2015). "Regions of eIF3e expression in brain glia were also characterized, demonstrating an upregulation in tumor microvessels and pseudopuncta." (PMID 37522921, 2023). "This study and others suggest that eIF3e normally functions as a tumor suppressor since the reduction of its expression results in enhanced mRNA stability and expression of the transcription factors and EMT regulators, Snail1 and Zeb2." (PMID 28083147, 2016). "The EIF3F and EIF3E have characteristics similar to tumor inhibitory factors, which inhibit the cell proliferation and promote apoptosis." (PMID 22734884, 2012). "In contrast, the high expression of wild-type eIF3e does not promote malignant transformation, suggesting that wild-type eIF3e may have a tumor suppressor effect while truncated eIF3e has oncogenic potential." (PMID 36360287, 2022). "While the role of eIF3e in translational control is not yet established, the studies in yeast support a tumor suppressor role in ameliorating oxidative damage associated with nutritional stress conditions." (PMID 32974334, 2020). "And high expression of eIF3E and eIF3J was observed more in patients with residual tumours (13/4 vs. 172/170, p = 0.0456) and without mutations in KRAS/EGFR/ALK (47/48 vs. 86/46, p = 0.0206), respectively." (PMID 31885740, 2019). "Notably, expression levels of most eIF3 subunits are upregulated in cancer, except for eIF3e and f, which are downregulated in tumour cells and may act as tumour suppressors." (PMID 34209750, 2021). "In contrast, high expression of EIF3E and PPIA were involved in lipid metabolism pathways, and they were also reported to take part in the proliferation of tumour cells." (PMID 37491740, 2023). "The eukaryotic translation initiation factors, namely, EIF1, EIF3E, EIF3H, EIF4G2, EIF5, and EIF6, were all upregulated in the brain metastasis-derived tumor cells." (PMID 33170151, 2020). "On the contrary, the overexpression of wild-type full-length eIF3e do not promote malignant transformation, indicating a possible tumor suppressor role for wild type eIF3e and an oncogenic potential of truncated eIF3e." (PMID 33148274, 2020). "Besides, nine eIF3 subunits beyond eIF3D were found aberrantly expressed in LUAD tissues and in which the expression levels of five subunits (eIF3B, eIF3C, eIF3E, eIF3H, and eIF3J) increased in LUAD patients with high tumour stage, implicating their roles in the maintenance or progression of LUAD." (PMID 31885740, 2019). "Unlike eIF3e, eIF3f is consistently shown to function as a tumor suppressor in pancreatic cancer." (PMID 28083147, 2016).
EIF3E also shares sentences with these, for which no sentence is quoted: colon cancer (2 papers); lung adenocarcinoma (2); lung carcinoma (2); Acute hepatitis (1); brain tumor (1); Cerebral ischemia (1); colon adenocarcinoma (1); diabetes (1); Dystonia (1); gastric adenocarcinoma (1); liver diseases (1); Neurological Disorder (1); non-small cell lung carcinoma (1); prostate carcinoma (1); triple-negative breast carcinoma (1).